CBL (Cbl proto-oncogene)
Diseases named in the same sentence as CBL in open-access papers (continued):
Sharing a sentence is not in itself a finding about the gene and the disease.
COVID-19 (1 paper, 2022). A disease caused by infection with severe acute respiratory syndrome coronavirus 2. "Additionally, an increase in the expression of MAP2K6, CBL and RUNX3 was observed in COVID-19-positive patients (p = 0.047; p = 0.00093; and p = 0.0044, respectively)." (PMID 36298734, 2022). "Bioinformatics analyses showed upregulation of MAP2K6, CBL, RUNX3, STAT1, and JAK2 in COVID-19-positive vs. -negative patients." (PMID 36298734, 2022).
cutaneous T-cell lymphoma (1 paper, 2016). "Because increased c-CBL blocks kinases that lead to activation induced cell death in cutaneous T-cell lymphoma cells, its knockdown promotes apoptosis of this neoplasm." (PMID 27472394, 2016). "We have recently shown that c-CBL is overexpressed in cutaneous T-cell lymphoma (CTCL) and modulates PLCγ-1-Fas apoptosis pathway signaling." (PMID 27472394, 2016).
endometrial adenocarcinoma (1 paper, 2021). "CBL is a proto-oncogene, encoding one of the ubiquitin ligase protein CBL involving in cell signaling, and causes a mutation in the lung, colon, endometrial adenocarcinoma, cutaneous, and breast cancer." (PMID 33968364, 2021).
endometrial cancer (1 paper, 2021). Primary or metastatic malignant neoplasm involving the endometrium (mucous membrane that lines the endometrial cavity). "As per our findings, we suggest CBL as an apt target for Nitroglycerin and novel drug design against Endometrial cancer." (PMID 34764329, 2021).
Epileptic encephalopathy (1 paper, 2014). A condition in which epileptiform abnormalities are believed to contribute to the progressive disturbance in cerebral function. "Using a targeted resequencing approach, we screened KCNT1, PIGQ, CBL and CSNK1G1 in a large cohort of epileptic encephalopathy cases from Australia." (PMID 24463883, 2014).
esophageal cancer (1 paper, 2024). A primary or metastatic malignant neoplasm involving the esophagus. "Previous studies have reported a pro-Tex role for CBL in diseases such as esophageal cancer, in which CBL interacts with SPRY1 to promote Tex, contributing a pro-cancer effect." (PMID 39239096, 2024).
germ cell tumor (1 paper, 2024). A benign or malignant, gonadal or extragonadal neoplasm that originates from germ cells. "Notably, the loss of copy neutrality of these heterozygous CBL mutations occurred due to acquired haploidy at 11q23 in three of the teratomas, suggesting a specific association between CBL mutations and the susceptibility to germ cell tumors." (PMID 39130630, 2024).
Inguinal hernia (1 paper, 2020). Protrusion of the contents of the abdominal cavity through the inguinal canal. "We discovered that PIK3R1, PTPN11, TGFBR1, CDC42, SOS1, and KRAS were the most essential inguinal hernia-causative proteins and UBC, GRB2, CTNNB1, HSP90AA1, CBL, PLCG1, and CRK were listed as the most commonly-involved downstream proteins." (PMID 31910207, 2020).
liver cancer (1 paper, 2023). An epithelial or non-epithelial malignant neoplasm that arises from the liver. "Overall, our study revealed a novel miR-22-3p/CBL/SPRY2/ERK axis that plays an important role in EMT, cell migration, and invasion of liver cancer cells." (PMID 36749775, 2023). "By inhibiting the expression of CBL, which stabilizes SPRY2, miR-22 indirectly upregulates SPRY2, thereby suppressing the epithelial-mesenchymal transition (EMT), cell migration, and invasion and decreasing the expression of liver cancer stem cell (CSC) marker genes." (PMID 36749775, 2023).
lung fibrosis (1 paper, 2023). "The Net-M5 detected genes involved in lung fibrosis (CXCL8 and IL1B), VEGFA-VEGFR2 signaling (NR4A1 and CBL), and TGF-β signaling (JUNB and ATF3)." (PMID 38259488, 2023).
macrocytic anemia (1 paper, 2011). Anemia that is characterized by increased red blood cell volume. "CBL deficiency may present as macrocytic anemia, subacute combined degeneration of the spinal cord, or as neuropathy, but is often asymptomatic in older people." (PMID 21952034, 2011).
metastatic tumors (1 paper, 2023). "Next-generation sequencing showed that the primary and lung metastatic tumors shared 4 mutations: PTEN (p.P248Lfs*8), CTNNB1 (p.D32A), BCOR (p.N1425S) and CBL (p.S439N)." (PMID 37328769, 2023).
myeloid sarcoma (1 paper, 2025). A tumor mass composed of myeloblasts or immature myeloid cells. "The PDX 49 represents a unique case of myeloid sarcoma within this cohort, and retained STR, morphology and fusions (CBL – USP2, SMG5–CTSS, and KPNA1–CBFA2T2) identical to those of the original tumor." (PMID 40801203, 2025).
pancreatic adenocarcinoma (1 paper, 2016). "Interestingly, we found in-frame deletion pDM in two cancer genes WRN (c2305-2307; ACTAAAGAA > ACTAAA, pK506-E507 deletion, REDACT score: RED*cT) and CBL (c1506-1508; AATTATGAT > AATTAT, pY455-D456 deletion, REDACT score: REd*cT) in pancreatic adenocarcinoma (PAAD)." (PMID 27272679, 2016).
Parasite infection (1 paper, 2024). "KEGG enrichment analysis again enriched various pathways, including “Signaling by CSF3 (G-CSF),” “RHO GTPases Activate NADPH Oxidases,” “Regulation of signaling by CBL,” “Parasite infection,” “Neutrophil degranulation,” “Leishmania phagocytosis,” “Leishmania infection,” “Interleukin-3." (PMID 38629070, 2024).
potassium deficiency (1 paper, 2025). A condition due to decreased dietary intake of potassium, as in starvation or failure to administer in intravenous solutions, or to gastrointestinal loss in diarrhea, chronic laxative abuse, vomiting, gastric suction, or bowel diversion. "In the present study, protein–protein interaction network predictions revealed that MeAKT1.1 and MeAKT1.2 interact with both HAK5 and CBL1/9, suggesting that they may form a functional complex within the CBL–CIPK–Shaker module to regulate K+ uptake under potassium deficiency and abiotic stress." (PMID 40733450, 2025).
preeclampsia (1 paper, 2023). Preeclampsia is a hypertensive disorder of pregnancy that is characterized by new-onset hypertension with proteinuria presenting after 20 weeks of gestation, and depending on mild or severe forms may initially present with severe headache, visual disturbances, and hyperreflexia. "One study has shown that sustained hypoxia stress can repress the CBL expression and disrupt ubiquitin degradation, leading to impaired regulation of human trophoblasts, which is the main mechanism of preeclampsia." (PMID 36726727, 2023).
renal carcinoma (1 paper, 2026). A carcinoma arising from the epithelium of the renal parenchyma or the renal pelvis. "This suggests that curcumin effectively downregulates PTPN22/p-CBL Y700/PD-L1 and promotes T cell activation, thereby enhancing the tumor immune microenvironment and inhibiting renal cancer growth." (PMID 41522360, 2026). "In addition, we found that CBL overexpression effectively reduced the binding affinity between renal cancer cells and PD-1, an effect that was reversed by the overexpression of PD-L1." (PMID 41522360, 2026).
renal failure (1 paper, 2023). "Combining the most common mutations in cell signaling genes such as NRAS, CBL, and JAK2, the prevalence of these aberrations was 55% in CMML patients with renal failure as compared to 38% among patients with normal kidney function (p = 0.056)." (PMID 36282402, 2023).
retinal degeneration (1 paper, 2022). Degeneration of the retina. "This has been suggested to be attributed to inherited retinal degeneration associated with mutations in the CBL gene identified on whole-exome sequencing." (PMID 35887217, 2022).
Retinal dystrophy (1 paper, 2022). Retinal dystrophy is an abnormality of the retina associated with a hereditary process. "The systemic damage described and the ocular damage leading to the retinal dystrophy found could be the new characteristics of the ocular phenotype of CBL mutation-associated syndrome." (PMID 35887217, 2022).
squamous cell carcinoma (1 paper, 2025). A carcinoma arising from squamous epithelial cells. "Higher phospho-MAPK signaling was observed in the squamous cell carcinoma, consistent with the CBL mutation in the squamous cell carcinoma, though it could be driven by other mutations and/or microenvironmental factors." (PMID 41309580, 2025).
Sturge-Weber syndrome (1 paper, 2024). Sturge-Weber syndrome (SWS) is a rare congenital neurocutaneous disorder characterized by facial capillary malformations and/or cerebral and ocular ipsilateral vascular malformations that result in variable degrees of ocular and neurological anomalies. "Case reports have been published for GNB2, CBL and PIK3CD, describing patients with Sturge-Weber syndrome (GNB2) or lymphatic anomalies (CBL and PIK3CD)." (PMID 38778413, 2024).
triple-negative breast carcinoma (1 paper, 2024). An invasive breast carcinoma which is negative for expression of estrogen receptor (ER), progesterone receptor (PR), and human epidermal growth factor receptor 2 (HER2). "Similarly, in triple negative breast cancer, higher expression of UBASH3B promotes dephosphorylation and inactivation of CBL, which in turn loses ability to ubiquitinate and induce degradation of the epidermal growth factor receptor (EGFR), leading to accelerated cancer progression." (PMID 38461240, 2024).
uveal melanoma (1 paper, 2025). A melanoma derived from melanocytes of the uveal tract. "The STRING analysis performed in plasma samples of uveal melanoma patients for miR-155-5p showed that the molecules with the most interaction of the miR-155-5p were CBL and RAP1B proteins along with FOS and ETS1 (p value: 0.000399)." (PMID 38914847, 2025).
vascular occlusive disorder (1 paper, 2020). "Mutant CBL also promoted myofibroblast migration and proliferation via the PDGF receptor pathway, which could contribute to the vascular occlusive disorder observed in patients with heterozygous CBL mutations." (PMID 32637631, 2020).
tumor (107 papers, 2008 to 2026). "Patients with RAS-mutated tumours and CBL deletions showed worse OS (p = 0.004) and RFS (p = 0.044)." (PMID 41957139, 2026). "The results revealed that silencing of CBL partially rescued the promotion of tumor growth and reduction of CD8+ T cell infiltration caused by asparagine." (PMID 39964752, 2025). "Since the discovery of transforming CBL variants in human neoplasms, CBL has been viewed as a proto-oncogene." (PMID 39403923, 2024). "CBL which encodes an E3-ubiquitin ligase acts as a tumor suppressor in myeloid malignancies; also, its mutation is related to a Noonan syndrome-like disorder." (PMID 36437957, 2022). "CBL mutation-associated syndrome is characterized by phenotypic heterogeneity and variable developmental, tumor, and functional expressivity." (PMID 35887217, 2022). "Since the loss of CBL (sh-CBL) and CBL Mts result in loss of function of CBL, we used shRNA knockdown CBL cells of A549 and H358 to investigate tumor growth and metastasis in mouse models." (PMID 28835699, 2017). "Loss of heterozygosity (LOH) analysis of the CBL locus in tumor/normal pairwise tissues revealed significant LOH (27.3%, n=6/22)." (PMID 27244893, 2017). "CBL is a tumor suppressor gene on chromosome 11 encoding a multivalent adaptor protein with E3 ubiquitin ligase activity." (PMID 28589114, 2017). "Tumor #1, in addition to the mutations observed in Tumor #2, also harbored mutations in CBL (56.7%), PIKFIVE (21%), PIK3CA (38.2%), and PIK3R3 (25%)." (PMID 27057633, 2016). "Third, mutations in Cbl-proto-oncogenes (homologous to Cbl-c, or CBL2) are associated with changes in cancer risk in humans and mutations in related genes increase the ability to fight off tumours in mice." (PMID 27575253, 2016). "While NF1 and CBL mutations may contribute to tumor initiation in EOCRC, BRAF-driven signaling appears to play a more prominent role in LOCRC." (PMID 40282501, 2025). "Thus, CBL combines the properties of a tumor suppressor (loss of ubiquitination activity) with those of a proto-oncogene (recruitment and clustering of signaling components)." (PMID 39403923, 2024). "However, the relatively high VAF for each (with the exception of the CBL p.R420Q mutation in the peripheral blood) points toward a role for each mutation in the primary tumor cell type." (PMID 38199781, 2023). "In HNSCC tumor specimens, CBL was mutated and LOH was detected at the CBL locus." (PMID 27244893, 2017). "Using phospho-defective (Y700A) and phosphomimetic (Y700D) mutants, we demonstrate that Tyr700 phosphorylation status dictates CBL's capacity to target PD-L1 for destruction, thereby controlling immunosuppressive PD-L1 abundance in the tumor microenvironment." (PMID 41522360, 2026). "The H/L patients exhibited higher frequencies of NF1, CBL, MAPK3, and BMPR1A mutations, underscoring the need for further research into their functional roles in tumor progression." (PMID 40282501, 2025). "The findings revealed that in 8 out of the 22 CRC cases, there was an observable overexpression of c-CBL in the tumor samples." (PMID 39130630, 2024). "These roles represent the previously undiscovered facets of tumor-suppressive activity performed by c-CBL." (PMID 39130630, 2024). "CBL proteins exert anti-tumor effects by facilitating the degradation of several well-known tyrosine kinases with tumor-promoting roles, such as EGFR and HER2." (PMID 39342146, 2024). "Research has demonstrated that c-CBL possesses the ability to change the tumor microenvironment and impede the activity of the programmed cell death-1 (PD-1) protein." (PMID 39130630, 2024). "By promoting the degradation of receptor tyrosine kinases, c-CBL can exert tumor-suppressive effects and inhibit cancer progression." (PMID 39130630, 2024). "We examined the levels of c-CBL protein expression and tyrosine phosphorylation in various human tumor cell lines and surgical specimens." (PMID 39130630, 2024).
tumor (continued). "In an in vivo setting, the knockdown of Cool-1 substantially impedes the tumor-forming capabilities of GBM cells, which is closely associated with the alterations in c-CBL." (PMID 39130630, 2024). "The results showed that the tyrosine phosphorylation of c-CBL protein occurred in a tumor-specific manner in 12 (33%) of the analyzed tumor tissues." (PMID 39130630, 2024). "The restoration of ITSN-1s protein levels promotes the interaction between CBL E3 ubiquitin ligase and Eps8, leading to the increased ubiquitination of Eps8 tumor protein." (PMID 39130630, 2024). "The tyrosine phosphorylation of c-CBL protein was found to occur in a tumor-specific manner in 12 (33%) cases." (PMID 39130630, 2024). "Of the 36 surgical specimens taken from human tumor tissue, the c-CBL protein was shown to be tyrosine phosphorylated in 12 (33%) cases." (PMID 39130630, 2024). "In recent years, CBL has also played an important role in anti-tumor targeted drugs and many natural products, and there are still many related drugs under research or preclinical research." (PMID 39130630, 2024). "Examples include JAK2, CBL, NRAS, and NF1 of which CBL, a tumor suppressor with E3 ubiquitin ligase activity, is associated with reduced OS." (PMID 36831294, 2023). "And CBL played as an E3 ubiquitin ligase to inhibit receptor tyrosine kinase RTKs signaling pathway to further suppress tumor proliferation." (PMID 35027542, 2022). "Casitas B-lineage (CBL), an E3 ligase which has been studied to involve numerous cellular functions, including immune regulation, proliferation, metastasis, and tumor suppressor." (PMID 35027542, 2022). "It has been revealed that miR-124-3p functions as a tumor suppressor in BC by targeting CBL and MGAT5." (PMID 36038549, 2022). "CBL's capacity to control tumour growth inhibitory effects makes it a promising target for cancer therapy." (PMID 36000536, 2022). "Thirty-six tumour-related genes including ALK, AR, BRCA2, FANCD2 and CBL were found to be mutated in all the three disease groups." (PMID 36686473, 2022). "In a study of more than 10,000 cases from 33 cancer types, high tumor expression of a germline variant in an oncogene (AR, MET, RET, CBL, and PTPN11) was found in 33 patients." (PMID 32295625, 2020). "GEM implantation reduced the protein level of EGFR by promoting its c-CBL-mediated ubiquitination and degradation, thus inhibiting its downstream effects, such as tumor cell growth, angiogenesis, and metastasis." (PMID 32111094, 2020). "In 786-O primary tumor cell line we observed decrease expression of genes of insulin-associated proteins (IRS2, CBL), transcription regulators (AEBP1), PI3 kinase signaling (AKT1, BCL2L1) as well as lipid metabolism genes (ACOX1)." (PMID 30929166, 2019). "Based on our mutational data it is likely that the mutations that we detected in CBL were responsible for the enhanced expression of MET in HNSCC, since we determined high expression of Y1003 in our primary tumor specimens." (PMID 27244893, 2017). "A more rapid leukemic disease was observed upon conditional CBL deletion, using MMTV-Cre, on a CBL-B null background thus supporting a redundant but essential role of CBL and CBL-B as tumor suppressors in the context of myeloid leukemogenesis." (PMID 27276677, 2016). "In contrast to a potentially pro-oncogenic role of CBL proteins by promoting immune tolerance associated with tumorigenesis, a potentially opposite role of CBL proteins as tumor suppressors has emerged in the context of leukemogenesis." (PMID 27276677, 2016). "For example, some studies revealed a role of CBL in restricting tumor cell proliferation and invasion." (PMID 27842510, 2016).